VAPB (VAMP associated protein B and C)
Diseases named in the same sentence as VAPB in open-access papers (continued):
Sharing a sentence is not in itself a finding about the gene and the disease.
neurodegenerative disease (continued). "Despite these limitations, some of the mechanisms regulating the VAPB–PTPIP51 tethers are now being revealed and these have direct implications for neurodegenerative diseases." (PMID 26899735, 2016). "Thus, one possibility is that some neurodegenerative disease insults including familial mutant TDP43, FUS, C9orf72 derived toxic DPRs and Tau activate GSK3β which phosphorylates VAPB and/or PTPIP51 to disrupt their binding." (PMID 40045432, 2025). "Here we review the roles of VAPB and PTPIP51 in ER-mitochondria signaling and the mechanisms by which neurodegenerative disease insults may disrupt the VAPB-PTPIP51 interaction." (PMID 40045432, 2025). "A proper understanding of the mechanisms that regulate VAPB-PTPIP51 binding and tethering functions is thus important for comprehending many normal aspects of cell physiology but also for determining how abnormal ER-mitochondria signaling contributes to neurodegenerative diseases." (PMID 40045432, 2025). "Additionally, the overexpression of VAPB or PTPIP51 has been found to enhance ER–mitochondria signaling and promote synaptic signal transmission, suggesting the potential of targeting MAMs for therapeutic interventions in neurodegenerative diseases like ALS/FTD." (PMID 38584329, 2024). "The mechanisms by which different physiological inputs alter VAPB-PTPIP51 binding to dynamically regulate ER-mitochondria signaling and how this is disrupted in neurodegenerative diseases are not properly understood." (PMID 40045432, 2025).
infection (14 papers, 2010 to 2025). The state of being infected such as from the introduction of a foreign agent such as serum, vaccine, antigenic substance or organism. "Certain vapB-encoded antitoxins were reported to be induced during infection of human macrophages (Rv0550c, Rv2009, Rv2547 and Rv3321c)." (PMID 21738782, 2011). "Intermediately virulent (VapB-positive) R. equi has been reported to cause fatal cavitary pneumonia because of secondary infections in immunocompromised hosts, such as AIDS patients." (PMID 20445784, 2010). "Interestingly, in Sinorhizobium meliloti, a VapB/VapC TA system was implicated in cell growth during symbiotic infection." (PMID 38842312, 2024). "The expression of both the vapB and vapC genes from two vapBC modules increased immediately upon infection and remained at a high level until 24 hours post-infection (hpi), followed by a decline to a low level." (PMID 40737303, 2025). "Addition of recombinant VapB (rVapB) to the infection media promoted multiplication of the plasmid-less strain 103– much less than did rVapA." (PMID 36786596, 2023). "In growth analyses of HSV-1 on the single and double KO RK13 cells, we were unable to observe the reported two-log10 reduction at 48 h post infection after siRNA-mediated knockdown of VAPB in HeLa cells." (PMID 34200728, 2021). "A study to examine the plasmid pattern of VapB-positive R. equi to evaluate any correlation between human infection and pig infection in each area was necessary to prove the source of infection." (PMID 20445784, 2010). "In this study, the vapB genes were examined as representatives of their respective vapBC operons, with their transcription profiles monitored over a 24-hour period following stimulation initiated at 12 hours post-infection (hpi)." (PMID 40737303, 2025). "It is important to note, however, that the increase in the NE covered a wide distribution, which might reflect different cells at different stages of infection or might reflect shuttling of VAPB if it is being recycled for repeated use at the NE." (PMID 30717447, 2019). "Total VAPB protein levels in the cell were constant during a time course of infection." (PMID 30717447, 2019). "PLA between VAPB and RMDN3 antibodies revealed an increased number of punctate PLA signals as the infection proceeded." (PMID 38620036, 2024). "The interaction of VAPB with a wide variety of proteins implicates VAPB in many cellular processes, such as ER-organelle tethering, lipid transfer, calcium homeostasis, membrane trafficking, unfolded protein response (UPR), cytoskeleton organization, autophagy, and infection." (PMID 41536906, 2025). "In addition, parallel infection of cells expressing neither VAPA nor VAPB showed no titer reduction, indicating that the minor decrease is most likely not due to the VAPB deficiency." (PMID 34200728, 2021). "Importantly, VAPB knockdown did not alter pUL34, calnexin or GM-130 localization during infection, arguing against an indirect effect of VAPB on cellular vesicles and trafficking." (PMID 30717447, 2019). "To test whether this was also true for VapB and VapN, we added rVapA, rVapB, or rVapN to macrophages, or we added bafilomycin A1 (BafA1), which is a potent inhibitor of the lysosome-acidifying ATPase, and quantified LT accumulation in the absence of an infection." (PMID 36786596, 2023). "In Thailand, infection by R. equi has been reported in patients with and without HIV infection in Chiang Mai, and 52 isolates from 69 sporadic cases collected between 1993 and 2001 were VapB-positive R. equi." (PMID 20445784, 2010).
cancer (7 papers, 2011 to 2025). A tumor composed of atypical neoplastic, often pleomorphic cells that invade other tissues. "To determine the causal role of VAPB in cancer, we overexpressed VAPB in mammary epithelial cells or stably knocked down VAPB in tumor cells." (PMID 23049696, 2012). "While extensively studied in neurodegeneration, VAPB has limited prior association with cancer." (PMID 41462933, 2025). "As VAPB overexpression is associated with poor patient survival, targeting VAPB-associated protein secretory pathway may provide novel targets for future pharmacological strategies in cancer therapy." (PMID 23049696, 2012). "As a potential Eph receptor ligand, the MSP domain of the VAPB protein could affect tumor growth and invasion through modulation of Eph receptor activity, which is commonly dysregulated in cancer." (PMID 23049696, 2012). "Although VAPB was implicated in a wide range of cellular processes, its function in cancer has not been characterized." (PMID 23049696, 2012). "In addition to familial ALS, VAPB expression has been observed with cancer." (PMID 23049696, 2012). "This discovery opens up a number of exciting avenues for future studies of both full length VAPB and the secreted MSP domain in cancer." (PMID 23049696, 2012). "The results showed that CERS2, VAPB, GPAA1, and ST3GAL1 were widespread CNVs in pan-cancer." (PMID 36059802, 2022). "Despite strong indications of the consequences of VAPB expression in cancer, a direct role of VAPB in tumor growth has not been investigated." (PMID 23049696, 2012).
tumor (5 papers, 2012 to 2025). "KD cells with re-expression of VAPB restored tumor spheroid size and irregular morphology, demonstrating that phenotypes induced by shRNAs are VAPB specific and not due to off-target effects." (PMID 23049696, 2012). "In contrast to the morphology of vector control spheroids, which displayed disorganized and irregular structures with protrusions, knockdown of VAPB resulted in much smaller and more compact tumor spheroids." (PMID 23049696, 2012). "Overexpression of VAPB in mammary epithelial cells increased cell growth, whereas VAPB knockdown in tumor cells inhibited cell proliferation in vitro and suppressed tumor growth in orthotopic mammary gland allografts." (PMID 23049696, 2012). "To understand the mechanisms through which VAPB enhances proliferation, we investigated potential links between VAPB and signaling molecules relevant to tumor growth." (PMID 23049696, 2012). "Together, these data indicate that VAPB regulates tumor spheroid size by increased tumor cell proliferation." (PMID 23049696, 2012). "In our study, miR-143-3p, miR-221-3p, and miR-222-3p downregulation may lead to VAPB upregulation, potentially aiding tumor survival under ER stress or metabolic stress." (PMID 41462933, 2025). "Future studies should confirm its expression in prostate tissues, assess functional significance, and investigate mechanisms by which VAPB may contribute to tumor growth, such as interactions with androgen receptor signaling or lipid and calcium signaling." (PMID 41462933, 2025). "Our data suggest that VAPB functions to uphold proper cell cycle regulation, which could have notable implications for tumor growth." (PMID 37945695, 2023). "Furthermore, we conducted an analysis of VAPB expression in available datasets, comparing tumor tissue with non-tumor tissue." (PMID 37945695, 2023). "Indeed, we found that reconstituted VAPB expression significantly recovered the in vitro proliferation rates of the tumor cells as well as their ability of generating spheres." (PMID 37945695, 2023). "Accordingly, one mechanism by which VAPB promotes tumor cell proliferation could be through secretion of growth factors, cytokines, matrix metalloproteinases, as well as delivery of receptors to the cell surface." (PMID 23049696, 2012). "As an independent approach to determine whether VAPB is necessary for tumor cell growth, we knocked down VAPB in MMTV-Neu cells." (PMID 23049696, 2012). "In contrast, knockdown of VAPB in MMTV-Neu tumor cells inhibited pAKT levels." (PMID 23049696, 2012). "Here, the PTPIP51/VAPB interaction pattern may be predictive for a more aggressive tumor biology." (PMID 30139932, 2018). "Similarly, VAPB also has a growth-stimulatory activity of tumor tissue that might be tied to increased activity of Akt when VAPB is highly expressed." (PMID 28603693, 2017). "Finally, we identified molecular mechanisms by which VAPB regulates tumor cell proliferation." (PMID 23049696, 2012). "Furthermore, as VAPB also functions in protein secretion and vesicle trafficking, tumor cells may rely on this pathway for receptor localization and growth factor secretion in order to sustain growth." (PMID 23049696, 2012). "Therefore further studies are needed to address whether perturbation in these mechanisms alters the phenotypes of tumor cells in relation to VAPB expression." (PMID 23049696, 2012). "First, overexpression of VAPB in MCF10A-HER2 cells enhances phosphorylation of AKT, whereas knockdown of VAPB in MMTV-Neu tumor cells inhibited pAKT levels." (PMID 23049696, 2012). "VAPB knockdown tumor cells failed to form tumors or formed very small, non-palpable tumors at five weeks post-transplantation, compared to parental or vector controls." (PMID 23049696, 2012).
movement disorder (1 paper, 2025). Neurological conditions resulting in abnormal voluntary or involuntary movement, which may impact the speed, fluency, quality and ease of movement. "We found that the KI mice displayed the downregulated protein level of mutant VAPB, cytoplasmic inclusions of the mutant VAPB in CSMNs, movement disorders, and progressive degeneration of CSMNs." (PMID 41536906, 2025).
VAPB also shares sentences with these, for which no sentence is quoted: amyotrophic lateral sclerosis type 8 (5 papers); hereditary spastic paraplegia (2); lateral sclerosis (2); multiple system atrophy (2); Parkinson’s- (2); Primary lateral sclerosis (2); primary open angle glaucoma (2); viral infection (2); animal disease (1); Arrhythmia (1); Bartter syndrome type 4 (1); bronchopneumonia (1); cognitive decline (1); dengue (1); depression (1); diabetic nephropathy (1); distal spinal muscular atrophy (1); Dystonia (1); glioblastoma (1); HCMV infection (1); heart failure (1); Huntington disease (1); hyperinsulinemic hypoglycemia (1); Marinesco Sjögren syndrome (1); metastatic tumor (1); neurological diseases (1); osteoarthritis (1); Paget's disease of bone (1); progressive bulbar palsy (1); protein misfolding disorder (1).
A further 9 diseases each share a sentence with VAPB in 1 paper.